ENSG00000270022 (RNA, U12 small nuclear)
Gene: Long non-coding RNA gene on chromosome 22 (42,614,636 to 42,626,375, forward strand). Ensembl gene ENSG00000270022.
Gene Ontology:
Molecular function: pre-mRNA branch point binding
Biological process: mRNA branch site recognition
Cellular component: U12 snRNP